IFIT1 (interferon induced protein with tetratricopeptide repeats 1)
Diseases named in the same sentence as IFIT1 in open-access papers (continued):
Sharing a sentence is not in itself a finding about the gene and the disease.
tumor (66 papers, 2009 to 2025). "In melanoma tumor cells, CARM1 ablation induced dsDNA breaks and cGAS-STING activation, together with the increased expression of several ISGs, including Irf7, Ifit1, Oasl1, and Tap1, and the enhancement of tumor cell susceptibility to cytotoxic T cells." (PMID 35493527, 2022). "In poorly cohesive gastric carcinomas, which are known for a poor prognosis and limited response and resistance to treatment, IFIT1 expression by tumor-associated neutrophils (TANs) promoted EMT, facilitated an exhausted phenotype of T cells and induced resistance to anti-PD1 immunotherapy." (PMID 40564154, 2025). "A combination of clinical cohorts, bioinformatics analyses, and functional/molecular experiments revealed that high infiltration of Interferon Induced Protein with Tetratricopeptide Repeats 1 (IFIT1) + tumor-associated neutrophils (TANs) is a distinguishing feature of PCC patients." (PMID 38898490, 2024). "Our co-expression analysis indicated a significant and strong positive correlation between the expression of all selected PARPs, OAS2 and IFIT1 in tumor tissue suggesting a coregulatory mechanism within the tumor microenvironment." (PMID 40646573, 2025). "Further, innate immune activation, including interferon β, IFIT1, and inflammatory factor IL-1β, was observed in HeLa tumor cells." (PMID 41392286, 2025). "Increased IFIT1 expression also positively correlates with advanced disease stage, higher tumor grade and poor overall survival in OSCC patients." (PMID 40564154, 2025). "In contrast, such PARP-immune gene co-expression was not evident in normal adjacent tissue samples displaying only a weak positive correlation between PARP14 and IFIT1 expression after CRT, suggesting a tumor tissue-specific association." (PMID 40646573, 2025). "The IFIT1 protein appears to exhibit either pro-oncogenic or tumor suppressor properties, depending on the cancer type." (PMID 40564154, 2025). "We observed significant upregulation of the transcriptional levels of Ifnb1, Ifit1, Ifit2, Ifit3, Irf7, and Mx1 in irradiated 4T1 tumor tissues and irradiated CT26, H22, and GL261 carcinoma cells." (PMID 40470716, 2025). "The expression analysis showed significant downregulation of IFITM1 in tumor tissue, while IFIT1 was upregulated in both tumor and normal tissue after CRT." (PMID 40646573, 2025). "Accordingly, the mRNA expression of IFNβ, CXCL10, ISG15, and IFIT1 in the tumor tissues was analyzed." (PMID 39170700, 2024). "First, the ability of IFIT1 + TANs to promote tumor growth in vivo was tested in a xenograft tumor model." (PMID 38898490, 2024). "We found that upregulation of IFIT1 resulted in a significant increase in tumor growth; however, this effect was reversed in mice carrying tumors with sh-IFIT1, confirming that IFIT1 promoted tumor growth through in vivo regulation of neutrophils." (PMID 38898490, 2024). "IFIT1 up-/down-regulated TANs or control cells were mixed with tumor cells (MKN45) and the mixture was injected into the subcutaneous tissue of BALB/c nude mice." (PMID 38898490, 2024). "We observed a significant increase in tumor size, tumor volume, and tumor weight in the oe-IFIT1 group compared to the control group, and these increases were significantly attenuated in the combined anti-PD1 group (P < 0.001)." (PMID 38898490, 2024). "On this basis, we demonstrated that local ZEB1 expression in tumor tissues promoted IFIT1 + TANs infiltration." (PMID 38898490, 2024). "This work highlights the role of IFIT1 + TANs in mediating the remodeling of the tumor immune microenvironment and immunotherapeutic resistance and introduces IFIT1 + TANs as a promising target for precision therapy of PCC." (PMID 38898490, 2024). "Concurrently, using univariate Cox regression analysis, the prognostic value of IFIT1 expression for OS was validated in an independent TCGA cancer cohort containing 9163 tumor samples." (PMID 38898490, 2024).
tumor (continued). "We conclude that KLF13 exerts an anti-tumor effect by negatively regulating the expression of IFIT1 in THCA." (PMID 37817224, 2023). "The contour plot showed that the four effective CD8+ T cell clusters (CD28+, Ifit1+, Ifng+, and Gzmf+ T cells) exhibited significantly higher anti-tumor capacity in Ero1aKO tumors compared with WT counterparts." (PMID 37769655, 2023). "The IFIT1+, SPP1+ and CCL4+ TANs were identified as pro-tumour, were associated with a poorer prognosis and had the highest levels of PD-L1 expression." (PMID 37534829, 2023). "IFIT1 and IFITM3 expression were related to several immune checkpoint molecules and tumor-associated macrophage markers." (PMID 35941292, 2022). "Western blot analysis of tumor tissues showed that COL8A1 knockdown reduced IFIT1 and IFIT3 expression, as well as EGFR phosphorylation." (PMID 35280763, 2022). "The ISGs, IFIT1 and IFIT3, are implicated in important functions in tumor development, and serve as biomarkers for various cancers." (PMID 35280763, 2022). "The expression of representative ISGs including MX1, OAS3, and IFIT1 was found to be significantly higher in tumor cells compared to stroma cells." (PMID 34400640, 2021). "Ifit1 surrogate expression enabled us to discriminate between tumor cell-intrinsic and stromal Stat1-Ido1 functions in bulk gene expression TCGA data." (PMID 32444775, 2020). "Our results show a novel mechanism by which entinostat initiates an IFIT1-STING-mediated potentiation of STAT4 via IRF1 to augment NK cell-mediated anti-tumor responses." (PMID 32499867, 2020). "In this context, a previous study showed that over-expression of IFIT1 in OSCC cells promote tumor growth and metastasis by activating EGFR signaling." (PMID 32961854, 2020). "Meanwhile, Abx treatment inhibited the expression of type I interferon (IFNβ), and ISGs (MX1, ISG15, and IFIT1) in small intestine and tumor tissues, validating its regulation on IRF3 activation." (PMID 33188184, 2020). "Ectopic expression of IFIT1 or IFIT3 in OSCC cells promoted tumor growth and metastasis by activating EGFR signaling." (PMID 31921891, 2019). "Consistent with the control group, p200 family members were also significantly affected in tumor-bearing p204 KO mice; p202 was dramatically induced, while p205b, Pydc3, and IfIT1 were reduced." (PMID 29691417, 2018). "We also demonstrate for the first time that HSP90 inhibition upregulates interferon response genes in the tumor, notably IFIT1, IFIT2 and IFIT3, both in vitro and in vivo." (PMID 28878208, 2017). "IFIT-silenced and control tumor cell lines were generated by simultaneously transducing tumor cells with IFIT1, IFIT2 and IFIT3 small hairpin RNAs (shRNA) or with scrambled shRNA, respectively." (PMID 28878208, 2017). "They found that four out of the five insensitive tumor cell lines expressed IFIT1 in the presence of the virus, whereas the remaining insensitive cell line and the sensitive one did not develop a type I IFN response." (PMID 26539644, 2015). "As a key ISG, IFIT1 plays a crucial role in antiviral immune responses and tumor progression." (PMID 40510586, 2025). "The increased expression of IFIT1 in macrophages may reflect an attempt to counteract immune suppression within the tumor microenvironment." (PMID 40510586, 2025). "In this cancer type, IFIT1 overexpression promotes tumor growth and metastasis through epithelial-mesenchymal transition (EMT), while its silencing leads to opposite effects, likely through enhanced p-EGFR (phosphorylated epidermal growth factor receptor) recycling." (PMID 40564154, 2025). "Notably, IFN T cells exist in the NPC_PT and NPC_LNM samples, where their highly expressed IFIT1 and IFIT3 genes have been proven to be associated with tumour growth and metastases." (PMID 39392128, 2024).
tumor (continued). "Finally, Cluster 8 was equally conserved across healthy and tumor-associated neutrophils and was enriched for IFN markers: Isg15, Rsad2, Ifit3, Ifit1, and Slfn4, a phenomenon previously reported in several scRNA-seq studies of neutrophils." (PMID 38358352, 2024). "Moreover, IFIT1 cytoplasmic expression was significantly down-regulated by KPT-9274, suggesting that KPT-9274 downregulates Wnt/β-Catenin pathway via a suppression of IFNGR1 and IFIT1, contributing to the anti-tumor effects." (PMID 38424218, 2024). "These facts reveal a complex signaling crosstalk in the PCC tumor microecology, but key among them may be the ZEB1 + tumor cells and IFIT1 + TANs." (PMID 38898490, 2024). "We next experimentally verified the effect of IFIT1 on anti-tumor immunity." (PMID 38898490, 2024). "In present study, we performed multiplexed IF staining experiment to preliminary explore whether IFIT1/IFIT3+ T cells play tumor‐promoting or cytotoxic roles in lymph node metastasis." (PMID 36709495, 2023). "In summary, our work suggests a mechanism whereby CXCL11 acts as a key mediator integrating CAFs and CAF-cohabitating cancer cells, and functions as an extracellular remodeler promoting HCC migration and metastasis through the activation of circUBAP2/miR-4756/IFIT1/3 in tumor cells." (PMID 33707417, 2021). "In particular, increased IFIT1 and IFIT3 expression has been correlated with improved therapeutic response to chemotherapeutics and immunostimulating agents and increased IFIT2 expression in the tumour tissues of patients was associated with improved patient survival." (PMID 36579897, 2023). "Since IFIT1 is able to reduce tumor cell growth both in vitro and in vivo, it is tempting to speculate that the strong chemerin effect on IFIT1 expression present in OVCAR-3 cells (16-fold up-regulation) could be another mechanism underlying the decreased growth of this cell line." (PMID 36077645, 2022). "For instance, IFIT1, IFIT3, IFI-16, ISG15, MX1, and OAS1 have been shown to have tumor-suppressive function." (PMID 40563638, 2025). "Taken together, our work provides evidence for the function of IFIT1 + TANs in PCC tumors and suggests that IFIT1 + TANs and ZEB1 + tumor cells play an important role in TME remodeling through multiple mechanisms of signaling crosstalk." (PMID 38898490, 2024). "In the present study, we reported that IFIT1 + TANs were stimulated by exogenous IFN-γ and reduced the number and function of tumor-infiltrating activated T cells." (PMID 38898490, 2024). "In line with this, enrichment of high PD-L1 expressing IFIT1+, SPP1+ and CCL4+ TANs in HCC tumours correlated with a poorer prognosis indicating a pro-tumour role for these clusters." (PMID 37534829, 2023). "In liver tumors, scRNA-seq analysis identified three pro-tumor TAN subsets (CCL4+ TANs, IFIT1+ TANs, and SPP1+ TANs) and one anti-tumor subset (APOA2+ TANs)." (PMID 38066642, 2023). "The six HCC TAN clusters; MMP8+, APOA2+, CD74+, IFIT1+, SPP1+ and CCL4+ can be characterised by predicted function and role in tumour development." (PMID 37534829, 2023). "The S100A12+, ISG15+ and TXNIP+ subtypes are found in peripheral blood, the ELL2+ and PTGS2+ mainly in adjacent liver and the MMP8+, APOA2+, CD74+, IFIT1+, SPP1+ and CCL4+ predominantly located in the tumour." (PMID 37534829, 2023). "Previous studies have reported that IFIT1 acts as an oncogene in various tumors, whereas its significance, as well as its involvement in KLF13 suppression of tumor progression, in THCA remains to be determined." (PMID 37817224, 2023). "On the contrary, the high expression of IFIT1 and IFIT3 in OSCC contributes to gefitinib's anti-tumor effect by enhancing p-EGFR recycling." (PMID 37980495, 2023). "We first confirmed that tumor tissues with chemohormonal treatment showed a higher level of IFN-stimulated genes, such as IFIT1, IFI44, CCL5, and IFNB, compared with treatment-naive tissues." (PMID 35836810, 2022).
tumor (continued). "We then analyzed tumor-infiltrating CD4 T cells and found an increased expression of interferon-beta (Ifnb1) and interferon-stimulated gene (ISG) transcripts (Ccl5, Ifit1, and Mx2) in cells isolated from mice treated with cGAMP compared with controls." (PMID 35091453, 2022). "The IFIT1, ISG15, IFITM1 and IFI27 genes are related to activation of the interferon gamma (IFNγ) response, suggesting possible inflammatory responses in NR tumour samples." (PMID 35053540, 2022). "Since PVSRIPO provoked type-I/III IFN responses in tumor tissue, we analyzed cell-intrinsic IFN responses by staining for the IFN-stimulated gene, IFIT1." (PMID 33767151, 2021). "Although IFIT2 belongs to the same family, it executes tumor suppressor functions, whereas IFIT1 and IFIT3 have tumor-promoting properties in OSCC." (PMID 31921891, 2019). "IFIT1 and IFIT3 promoted EGFR activation in OSCC cells and enhanced the tumor-preventive activity of gefitinib." (PMID 31921891, 2019). "The direct association of IFIT1 or IFIT3 with heat shock proteins (Hsp90α/β) suggests a unique mechanism of action of IFIT1 and IFIT3 that may be involved in activating Hsp90 and several of its downstream signaling regulators, which are crucial for OSCC tumor progression and drug resistance." (PMID 31921891, 2019). "We now show that IFIT2 and other family members IFIT1 and IFIT3, when overexpressed in tumor cells, enhance T-cell killing of tumor cells." (PMID 28878208, 2017). "An interferon gene signature was also present in the profiles derived from the tumor epithelium of the ER-positive tumors (e.g., STAT1, IFIT1, IFIH1, IFI27, ISG15, OAS1, OAS3, OASL) and ER-negative tumors (e.g., HLA-DQA1 and HLA-DQB1)." (PMID 19225562, 2009). "Based on flow cytometry analysis, anti-PD1 treatment significantly promoted the activation but suppressed the exhaustion phenotype of tumor-infiltrating cytotoxic CD8 + T cells in mice compared to controls, and these effects were reversed by oe-IFIT1 (P < 0.01)." (PMID 38898490, 2024). "The increased transcripts for EGR1, interferon-induced proteins (IFI6, IFIT1, IFIT3, IFIT5), and MHC class II (HLA-DRA) indicated strong stimulation of IFN signaling, which could result in activation of macrophages in the tumor microenvironment." (PMID 37834191, 2023). "To further investigate whether COL8A1-mediated tumor progression required IFIT1 and IFIT3 knockdown, we examined cell proliferation in COL8A1-overexpressing and IFIT1/IFIT3-silenced NSCLC cells." (PMID 35280763, 2022). "Mechanistically, treatment with entinostat was reported to increase chromatin accessibility of the IFIT1 gene promoter region, driving the epigenetic upregulation of the IFIT1-mediated IRF1, STAT4 and STING pathways, and resulting in increased NK cell cytotoxicity against tumor targets." (PMID 34777383, 2021). "IHC staining of human biopsies demonstrated IFIT1 expression in CRC cancer cells but not in the tumor stroma." (PMID 32444775, 2020). "Owing to an upregulation of interferon-inducible genes, including Ifit1, Ifit3 and Bst2, the EO771 and EO771.LMB tumours might correspond more closely to the interferon-rich subtype of human basal-like tumours." (PMID 25633981, 2015). "However, such genes as IFI27 (−4.38), SLC22A7 (−3.97), IFIT1 (−3.91), TGFB3 (−3.71), and IFN-α induced (−3.72) also had stronger suppression at the transcript level in HCC-R tumor tissues." (PMID 24377043, 2013). "This might explain why certain subtypes of IFN-activated TANs (such as IFIT1+ TANs) do not necessarily exhibit the anti-tumor characteristic of N1 TANs." (PMID 40461514, 2025). "Likewise, interferon response genes (including TLR3, MX1, RSAD2, IFI44, IFI27, IFIT1, and IFIT3), and chemokine genes (including CCL7, CXCL10, CXCR1, and CCL25) were significantly increased in PM-treated MM tumor tissues, whereas panobinostat showed minimal effects at equivalent doses." (PMID 40562746, 2025).
tumor (continued). "Likewise, mRNA levels of Ifit1 and Ifit2, two type I IFN-stimulated genes (ISGs), were also elevated in Ptgs2−/− tumors, indicative of enhanced type I interferon (IFN-α/β) signaling, which is central to immune-mediated tumor control." (PMID 26343581, 2015). "In addition a set of 15 proteins that participate in the antitumor immune response such as the tumor suppressors PSMB9, ERAP1 and TAP1 or the interferon-stimulated genes IFIT1 and MX1 were found down-regulated in CUL4A-overexpresing cells and up-regulated in CUL4A-silencing models." (PMID 24870930, 2014). "Comparison of all three sample types (fluid, tumor tissue and PBMCs) identified only 2 DE genes—CXCR4 and IFIT1—which do not show concordant expression between samples." (PMID 36428740, 2022).